DRAM2 (DNA damage regulated autophagy modulator 2)
Description:
Plays a role in the initiation of autophagy. In the retina, might be involved in the process of photoreceptor cells renewal and recycling to preserve visual function. Induces apoptotic cell death when coexpressed with DRAM1.
Synonyms: TMEM77; MGC54289; PRO180; WWFQ154; RP5-1180E21.1; CORD21
Tractability: Antibody: UniProt places it where antibodies can reach, with medium confidence; UniProt predicts a signal peptide or a membrane-spanning region; its Gene Ontology location is reachable by antibodies, with medium confidence.
Gene: Protein-coding gene on chromosome 1 (111,115,884 to 111,140,225, reverse strand). Ensembl gene ENSG00000156171.
Subcellular location: Lysosome membrane; Photoreceptor inner segment; Apical cell membrane
Subcellular location (Human Protein Atlas): Golgi apparatus; Vesicles
Gene Ontology:
Biological process: photoreceptor cell maintenance; regulation of autophagy; visual perception
Cellular component: cytoplasm; Golgi apparatus; lysosome; apical plasma membrane; photoreceptor inner segment; lysosomal membrane
Genetic constraint (gnomAD): Loss-of-function variants: 22 observed, 28.16 expected, observed/expected ratio (o/e) 0.78, 90% interval 0.56 to 1.12. The upper end of that interval is the gene's LOEUF score, 1.12, which puts it in group 4 of 6, group 1 being the genes least tolerant of losing a copy. Missense variants: 271 observed, 289.48 expected, observed/expected ratio (o/e) 0.94, 90% interval 0.85 to 1.03. Synonymous variants: 89 observed, 101.72 expected, observed/expected ratio (o/e) 0.87, 90% interval 0.74 to 1.04.
Homologues: Orthologues: chimpanzee DRAM2 (100% identical), rabbit DRAM2 (94% identical), pig DRAM2 (91% identical), guinea pig DRAM2 (86% identical), mouse Dram2 (86% identical), rat Dram2 (86% identical), dog DRAM2 (82% identical), zebrafish dram2b (54% identical), zebrafish dram2a (49% identical), Drosophila melanogaster CG4025 (32% identical), Caenorhabditis elegans C33A11.2 (28% identical), Caenorhabditis elegans W03A5.2 (18% identical). Paralogues in human: DRAM1 (37% identical), TMEM150B (24% identical), TMEM150A (22% identical), TMEM150C (22% identical).